TOP2A (DNA topoisomerase II alpha)
Diseases named in the same sentence as TOP2A in open-access papers (continued):
Sharing a sentence is not in itself a finding about the gene and the disease.
gastric cancer (24 papers, 2007 to 2025). A primary or metastatic malignant neoplasm involving the stomach. "In the present study, it was determined that azomethine group compounds in AGS gastric cancer, contrary to the mentioned studies, significantly reduced TOP2A gene expression levels and were associated with a good prognosis for gastric cancer." (PMID 37895364, 2023). "In patients with stage II/III gastric cancer, TOP2A, GGH, and PECAM1 levels in primary tumors are linked to high risk of hematogenous, lymph node, and peritoneal recurrence, respectively." (PMID 28915696, 2017). "Amplifications of the human TOP2A locus is associated with somatic mutations in subsets of breast, bladder and gastric cancers." (PMID 22111588, 2011). "In another study, FAM230B was reported to be upregulated in gastric cancer and promotes tumor metastasis and growth by sponging miR-27a-5p to upregulate TOP2A." (PMID 36262247, 2022). "FAM230B was highly upregulated in gastric cancer and it upregulates TOP2A by sponging miR-27a-5p to promote both tumor growth and metastasis." (PMID 35287554, 2022). "In the enrichment analysis with “Enrichr” online tool, Gastric Cancer Network2 was of the lowest p-value containing TOP2A and RFC3 genes involved in DNA replication process." (PMID 34249670, 2021). "PECAM1 mRNA levels were higher in diffuse-type than in intestinal-type gastric cancer, whereas the opposite was true for TOP2A and GGH expression (P < 0.0001)." (PMID 28915696, 2017). "CDC2+DPT and CDC2+TOP2A are found to be good discriminators for five cancer types, namely breast, colon, lung, prostate and stomach cancers." (PMID 21060876, 2010). "In this study, we demonstrated that EGFR, HER2, and TOP2A were overexpressed and amplified in gastric carcinomas from Chinese patients; similar results were observed in Western countries and in other Asian countries." (PMID 19061514, 2008). "A combined investigation of the gene status of EGFR, HER2, and TOP2A should facilitate the identification of a target therapeutic regimen for gastric carcinoma patients." (PMID 19061514, 2008). "Herein, we investigated the gene status of EGFR, HER2, and TOP2A in Chinese gastric carcinoma patients." (PMID 19061514, 2008). "In the current study, EGFR, HER2, and TOP2A gene copy numbers and corresponding levels of protein expression in Chinese gastric carcinomas were determined by FISH and immunohistochemistry(IHC), respectively." (PMID 19061514, 2008). "This study documented alterations in protein expression and gene copy number for EGFR, HER2, and TOP2A in Chinese patients with gastric carcinoma." (PMID 19061514, 2008). "In addition, TOP2A expression level was significantly negatively correlated with the numbers of macrophages in gastric cancer tissues." (PMID 33150086, 2020). "Therefore, it is reasonable to focus on EGFR, HER2, and TOP2A overexpression and/or gene amplification when developing therapeutic strategies to target gastric carcinomas." (PMID 19061514, 2008). "The correlation between EGFR, HER2, and TOP2A in gastric carcinomas was determined." (PMID 19061514, 2008). "We were unable to determine a relationship between the alterations in EGFR, HER2, TOP2A, chromosome 7, or chromosome 17 and the clinicopathologic characteristics of gastric carcinoma; this is in contrast to previous reports, and may be due to different sample numbers and different populations." (PMID 19061514, 2008). "Previous studies have reported that TOP2A is characterized by PARP-1 cleavage and caspase-3 activation in gastric cancer, thus triggering the apoptosis pathway." (PMID 37781045, 2023). "Thus, the same may be said of co-amplification of ERBB2 and TOP2A in gastric cancer." (PMID 28915696, 2017). "Therefore, the present study was to investigate whether the genes ERCC1, BRCA1, TYMS, RRM1, TUBB3, STMN1 and TOP2A are underlying biomarkers for patients with gastric cancer, which, to our knowledge, has not been performed." (PMID 28056823, 2017).
gastric cancer (continued). "In our study, TOP2A amplification was not a frequent event in gastric carcinoma; this may be the reason why anthracycline therapies have not been effective in targeting gastric carcinomas." (PMID 19061514, 2008).
leukemia (24 papers, 2012 to 2025). A malignant (clonal) hematologic disorder, involving hematopoietic stem cells and characterized by the presence of primitive or atypical myeloid or lymphoid cells in the bone marrow and the blood. "Studies have shown that in etoposide-resistant leukemia cells there are two isoforms of this enzyme, TOP2α/170 and TOP2α/90, which appear to be the product of alternative RNA processing." (PMID 35715750, 2022). "The specific case of TOP2α exon 19/intron 19 splice site editing is discussed in etoposide-resistant human leukemia K562 cells as a tractable strategy to circumvent acquired TOP2α-mediated drug resistance." (PMID 35804920, 2022). "TOP2α/170 is the target of anticancer drugs, but it appears that the expression of this isoform decreases in etoposide-resistant leukemia cells, while the expression of TOP2α/90 increases significantly." (PMID 35715750, 2022). "It is now apparent that a form of alternative polyadenylation (APA), designated as intronic polyadenylation (IPA), plays a major role in mediating resistance to TOP2α inhibitors/poisons in several human leukemia cell lines (HL-60, CEM, and K562)." (PMID 35804920, 2022). "TOP2A is highly expressed in 721_B lymphoblasts (leukemia cells) and in the testis." (PMID 40746357, 2025). "Together, these results demonstrate that CRISPR/Cas9/HDR editing of the TOP2α gene to abrogate normal RNA processing results in etoposide resistance in human leukemia K562 cells and further supports the dual role of TOP2α/170 and TOP2α/90 isoforms as sensitivity/resistance determinants." (PMID 35617303, 2022). "Additionally, the analysis reveals that drugs approved to treat either leukaemia or Kaposi’s sarcoma cluster, share the topoisomerase II alpha (TOP2A) enzyme as target." (PMID 36085310, 2022). "Therefore, TOP2α interfacial inhibitors/poisons (e.g., etoposide, mitoxantrone, and anthracyclines), are efficacious in the treatment of a variety of leukemias, lymphomas, and solid tumors." (PMID 35804920, 2022).
bladder cancer (21 papers, 2010 to 2025). "Amplification of TOP2A, encoding a type II isomerase, has been reported for a multitude of neoplasms including breast, gastric, and pulmonary cancers, and isolated TOP2A amplifications have been found in urinary bladder cancers and acute lymphoblastic leukaemias." (PMID 22292074, 2012). "In urinary bladder cancer, TOP2A has been suggested to be one of the potential therapeutic targets and a prognostic biomarker, as its overexpression has been strongly linked to the progression of the tumor stage and poor prognosis." (PMID 40137900, 2025). "TOP2A is found to be upregulated in bladder cancer samples, particularly in high-grade and advanced-stage tumors, as compared to normal epithelial tissue." (PMID 39456780, 2024). "Propofol modulates the proliferation, invasion, and migration of bladder cancer cells through the miR-145-5p/TOP2A axis." (PMID 36077665, 2022). "In bladder cancer, studies indicate that the expression of TOP2A in tumour cells is closely related to the efficacy of intravesical instillation of anthracyclines." (PMID 35711974, 2022). "In the present study, the cell toxicity experiments showed that bladder cancer cells with high expression of TOP2A significantly inhibited cancer growth compared with cells with low expression." (PMID 35711974, 2022). "TOP2A is the primary target of doxorubicin, which is an important chemotherapeutic drug for bladder cancer." (PMID 31216997, 2019). "We also assessed the potential effect of TOP2A knockdown on bladder cancer cell migration and invasion, which were two critical steps accounted for cancer progression and metastasis." (PMID 31216997, 2019). "We investigated the level of TOP2A in several bladder cancer cell lines, J82 and 5637 cells had relative higher TOP2A expression." (PMID 31216997, 2019). "HMGB3 promotes cell proliferation in bladder cancer and interacts with TOP2A and TOP2B, two targets for some anticancer agents." (PMID 28212608, 2017). "Further studies are needed to confirm whether a relationship exists between HER-2 and TOP2A in bladder cancer." (PMID 35711974, 2022). "We thus explored whether TOP2A could serve as a marker of response to doxorubicin in bladder cancer." (PMID 31216997, 2019). "A Pearson correlation analysis between TOP2A mRNA and protein in bladder cancer samples." (PMID 31216997, 2019). "Among them, TOP2A, CDC20, CDCA5 and UBE2C all act as oncogenes in bladder cancer and promote tumor progression." (PMID 36932399, 2023). "According to the CCK-8 assay results, TOP2A expression level was not correlated with the sensitivity of bladder cancer cell lines to doxorubicin." (PMID 31216997, 2019). "Furthermore, we found that TOP2A played a major role in BLCA by regulating proliferation, invasion and survival of bladder cancer cells." (PMID 31216997, 2019). "In the present study, we showed that TOP2A knockdown induced doxorubicin resistance in J82 cells, however, the sensitivity of different bladder cancer cell lines to doxorubicin was not significantly correlated with the expression level of TOP2A." (PMID 31216997, 2019). "In the present study, we found that knockdown of TOP2A could significantly inhibit the proliferation of bladder cancer cells and non-cancerous urothelial cells, which revealed the essential role of TOP2A in cell proliferation." (PMID 31216997, 2019).
non-small cell lung carcinoma (18 papers, 2013 to 2026). A group of at least three distinct histological types of lung cancer, including non-small cell squamous cell carcinoma, adenocarcinoma, and large cell carcinoma. "Our study established a model based on significant co-expression of TOP2A genes, which significantly correlated with mutational load and immunotherapy outcomes in patients with non-small cell lung cancer." (PMID 37407689, 2023). "Another two study showed that high expression of TOP2A was associated with poor prognosis of non-small cell lung cancer and clear cell renal cell carcinoma." (PMID 36288358, 2022). "In the study “The role of TOP2A in immunotherapy and vascular mimicry in non-small cell lung cancer and its potential mechanism” there were 141 patients." (PMID 40786517, 2025). "TOP2A expression increases in various tumors, particularly non-small cell lung cancer, where its expression correlates with tumor differentiation, TNM staging, and lymph node metastasis." (PMID 40777026, 2025). "In contrast, the role of TOP2A in the immunotherapy of non-small cell lung cancer as well as in Vasculogenic mimicry (VM) formation and its potential mechanisms are unclear." (PMID 37407689, 2023). "We further validated the role of TOP2A in regulating apoptosis and cycle in non-small cell lung cancer using apoptosis and cell cycle assays." (PMID 37407689, 2023). "The aim of this study was to investigate the role of TOP2A in proliferation, skeleton regulation, motility and VM production in non-small cell lung cancer and its mechanisms by using bioinformatics tools and molecular biology experiments." (PMID 37407689, 2023). "In conclusion, the current study links TOP2A overexpression, plasticity and motility of non-small cell lung cancer cells, immunotherapy, and the formation of VM." (PMID 37407689, 2023). "To further investigate the role of TOP2A in non-small cell lung cancer angiogenesis, we explored the intrinsic connection between TOP2A expression pattern and tumor cytoskeleton and motility using GSEA based on GEO and TCGA databases." (PMID 37407689, 2023). "TOP2A plays an important role in regulating immunotherapy and VM formation in non-small cell lung cancer by regulating the expression of the classical WNT ligand Wnt3a and the immune checkpoint PD-L1." (PMID 37407689, 2023). "TOP2A is an ideal candidate as miR-144-3p target in non-small cell lung cancer, while MiR-144-3p expression is significantly correlated with lymph node metastasis and vascular invasion." (PMID 31992202, 2020). "Moreover, TOP2A’s role in non-small cell lung cancer (NSCLC) has been investigated in relation to immunotherapy and vasculogenic mimicry." (PMID 40290723, 2025). "Although TOP2A has been shown to play a key role in tumors, it is still of practical importance to investigate the specific mechanisms of TOP2A's role in immune infiltration, immunotherapy and VM formation in non-small cell lung cancer." (PMID 37407689, 2023). "Among them, DLGAP5 could physically interact with PBK, TOP2A, and CDK1, and all mitosis-associated proteins correlated with poor prognosis for non-small cell lung cancer patients." (PMID 32426332, 2020). "TOP2A is related to brain metastasis for non-small-cell lung cancer." (PMID 28678795, 2017). "A multicenter next generation sequencing and gene expression study of ~17,000 unmatched primary tumors from non-small cell lung cancer (NSCLC), breast cancer and melanoma demonstrated higher TOP2A expression in brain metastases." (PMID 30886831, 2019). "It has been reported that the knockdown of USP15 results in the expression decrease in the topoisomerase II α (TOP2A) protein, instead of mRNA, in the human non-small cell lung cancer cell line A549, indicating that USP15 regulates TOP2A to maintain genome integrity." (PMID 35203682, 2022).
acute myeloid leukemia (14 papers, 2010 to 2024). Acute myeloid leukemia (AML) is a group of neoplasms arising from precursor cells committed to the myeloid cell-line differentiation. "And another analysis performed by GEPIA also showed consistent results that TOP2A was broad-spectrum up-regulated in various human tumors except for acute myeloid leukemia." (PMID 31528121, 2019). "However, the expression of TOP2A was lower in acute myeloid leukemia (LAML) compared with normal tissues (p < 0.001), and we did not obtain a significant difference in testicular germ cell tumors (TGCT)." (PMID 35778520, 2022). "It had been shown that etoposide treatment to patients can induce acute myeloid leukemia (t-AML), which is attributed to TOP2B-, but not TOP2A-mediated DNA damage that disrupts the mixed lineage leukemia (MLL) gene and MLL associated genes in benign bone marrow cells." (PMID 33598437, 2020).
lymphoma (13 papers, 2008 to 2024). A malignant (clonal) proliferation of B- lymphocytes or T- lymphocytes which involves the lymph nodes, bone marrow and/or extranodal sites. "To analyze the underlying cause of acquired resistance to CX-5461 in Eμ-Myc lymphoma, we performed WGS on resistant tumors and identified Top2α as one of the most recurrently mutated genes." (PMID 39062087, 2024). "In lymphoma, knockdown of TOP2A was found to reduce DNA damage and enable resistance to doxorubicin treatment." (PMID 36506091, 2022). "Lastly, TOP2A encodes a direct target of doxorubicin, a drug in the standard CHOP regimen of lymphoma therapy." (PMID 24130802, 2013). "This hypothesis has been supported through in vivo evidence that TOP2A expression can dictate DOX efficacy in a murine lymphoma model whereby the knockdown of TOP2A conferred DOX-resistance." (PMID 37047696, 2023). "The difference in the expression patterns of genes between the healthy and DLBCL samples in the canine dataset highlighted important lymphoma-specific up-regulated genes including DHFR, MS4A1, MYC, POLA1, POLE, RRM1, TOP2A and TYMS." (PMID 24023754, 2013). "To investigate whether CX-5461 Pol I inhibitory activity could be modulated by the level of Top2α protein, we measured the effect of CX-5461 on the rate of rRNA synthesis in T2AWT and T2A+/K1266 lymphoma cells using metabolic labelling." (PMID 39062087, 2024).
breast tumors (12 papers, 2008 to 2023). "It has been demonstrated that amplification of ERBB2 in BC cell lines and in primary breast tumors is associated with simultaneous amplification or deletion of the TOP2A gene." (PMID 18702822, 2008). "TOP2A expression in breast tumors has been reported to be associated with Ki-67 expression." (PMID 37895364, 2023). "TOP2A vaccination greatly increased the abundance of the anti-tumor EM-like CD8 + T cells in the breast tumor microenvironment (TME)." (PMID 37880313, 2023). "Here, we identified overexpression of the TOP2A gene in both mouse breast tumor cell lines and human TNBC cancer samples." (PMID 37880313, 2023). "We found that the TOP2A gene was overexpressed in various mouse breast tumor cell lines and human TNBC and lung tumors." (PMID 37880313, 2023). "TOP2A, topoisomerase II alpha, functioning as an enzyme relaxing DNA supercoils, has long been used as a cancer proliferation marker and applied for breast tumor subtyping." (PMID 28754978, 2017). "In patients that are treated with AC-based chemotherapy, breast tumors with TOP2A amplification show a trend towards a better disease free survival than tumors lacking this amplification." (PMID 26022247, 2015). "We therefore developed a Single Nucleotide Polymorphism (SNP) assay to evaluate allelic imbalance at the HER2/TOP2A locus in three different entities of primary breast tumors." (PMID 26022247, 2015). "In contrast, TOP2A expression is restricted to the much smaller subset of proliferating (i.e. Ki67-positive) cells of breast tumors." (PMID 25406834, 2014). "In one published analysis of a large collection of primary breast tumor samples, TOP2A alterations were reported in 23% of all tumors, regardless of their ERBB2 status: 12% had TOP2A amplification and 11% had TOP2A deletion." (PMID 18702822, 2008). "Patients with TOP2A amplified breast tumors seem to benefit from adjuvant AC-based chemotherapy." (PMID 26022247, 2015). "Here we conducted a retrospective study to determine whether the amplicon pattern, including amplification or deletion of TOP2A correlates with clinico-pathologic characteristics of breast tumors, markers of proliferation, and the clinical outcome of patients with ERBB2-amplified BC." (PMID 18702822, 2008). "Similar to the breast tumor samples, we observed increased frequencies of CD4 + Th1 cells after TOP2A vaccination." (PMID 37880313, 2023). "The breast tumor tissues from patients ERPR+ 4, 5 and 8–13 showed a stable HER2/TOP2A locus, IHC scores were 0–1+, SISH ratios ranged from 1.0–1.5 and a TC% was 50–70 %." (PMID 26022247, 2015). "We have confirmed that gene amplification, including that of TOP2A, occurs only in patients with HER2-amplified breast tumors." (PMID 21288332, 2011). "TOP2A vaccine treatment significantly increased the proportion of cDC in breast tumor tissues but not in lymph nodes." (PMID 37880313, 2023). "We identified both neutrophil subsets in breast tumor tissues and found that TOP2A vaccine treatment did not change the proportions of these two subsets." (PMID 37880313, 2023). "TOP2A vaccine treatment significantly increased the abundance of cytotoxic DNT cells, while the treatment decreased the proportion of innate DNT cells in mouse breast tumor tissues." (PMID 37880313, 2023). "TOP2A aberrations (amplification or deletions) occur in less than 10% of ERBB2 non-amplified breast tumors." (PMID 18702822, 2008).
clear cell renal cell carcinoma (11 papers, 2014 to 2025). "In addition, high TOP2A expression has also been reported in patients with advanced gallbladder carcinoma 63, clear cell renal cell carcinoma 64 and HCC 65 with a significantly increased risk of death." (PMID 31737106, 2019). "Higher TOP2A expression has been related with proliferation and metastasis in kidney clear cell carcinoma, a type of cancer that exhibits a diverse therapeutic response to immune checkpoint inhibitors." (PMID 39885205, 2025). "SNHG3 activates the progression of clear cell renal cell carcinoma via regulating the expression of miR‐139‐5p and as a result to up‐regulate TOP2A expression." (PMID 32248648, 2020).